Y_RNA (Y RNA )
Gene: Miscellaneous RNA gene on chromosome 1 (24,625,411 to 24,625,513, reverse strand). Ensembl gene ENSG00000239106.
Homologues: Orthologues: chimpanzee Y_RNA (94% identical), macaque Y_RNA (70% identical), pig Y_RNA (66% identical). Paralogues in human: Y_RNA (82% identical), RNY1P1 (81% identical), RNY1P5 (81% identical), Y_RNA (80% identical), Y_RNA (79% identical), RNY1P11 (78% identical), Y_RNA (78% identical), Y_RNA (77% identical), Y_RNA (76% identical), Y_RNA (75% identical), RNY1 (74% identical), Y_RNA (74% identical), and 90 more.